RNU6-635P (RNA, U6 small nuclear 635, pseudogene)
Gene: Small nuclear RNA gene on chromosome 4 (103,924,540 to 103,924,641, forward strand). Ensembl gene ENSG00000252460.
Homologues: Orthologues: chimpanzee U6 (98% identical), macaque U6 (96% identical), dog U6 (69% identical), rat LOC120096751 (64% identical). Paralogues in human: RNU6-753P (79% identical), RNU6-820P (79% identical), RNU6-15P (77% identical), RNU6-166P (77% identical), RNU6-41P (77% identical), RNU6-44P (77% identical), RNU6-536P (77% identical), RNU6-562P (77% identical), RNU6-589P (77% identical), RNU6-73P (77% identical), RNU6-1013P (76% identical), RNU6-1152P (76% identical), and 1289 more.